SHBG (sex hormone binding globulin)
Diseases named in the same sentence as SHBG in open-access papers (continued):
Sharing a sentence is not in itself a finding about the gene and the disease.
type 2 diabetes (continued). "The inverse association between SHBG and type 2 diabetes is consistent between studies, and females and males, which supports our findings." (PMID 35218343, 2022). "In the past decades, however, serum SHBG has also been inversely associated with several metabolic disorders, including obesity, non-alcoholic fatty liver disease, and type 2 diabetes." (PMID 35132570, 2022). "This MR study suggests robust associations of SHBG with a wide range of diseases, including hypertension, type 2 diabetes, diabetic complications, coronary atherosclerotic outcomes, gout, benign and malignant neoplasm of uterus, varicose veins and fracture." (PMID 35218343, 2022). "Low serum SHBG concentrations in overweight individuals are a biomarker for metabolic syndrome and are predictive of type 2 diabetes (T2D) and CVD risk." (PMID 33514384, 2021). "Increased fetuin and deceased SHBG systemic levels are strongly associated with metabolic syndrome and type 2 diabetes development." (PMID 33536069, 2021). "The two most famous large long-term studies, the MRFIT and MMAS, suggest that low TT, FT, and SHBG are independent risk factors for the later development of type 2 diabetes." (PMID 34966822, 2021). "Contrary phenomenon was observed for SHBG, in which low serum levels correlate with increased susceptibility of type 2 diabetes development." (PMID 33536069, 2021). "For example, low levels of sex hormone binding globulin (SHBG) occurring when estrogen levels are low have been shown to be associated with the MetS and type 2 diabetes in both men and women." (PMID 33081027, 2020). "Recent studies found that lower SHBG was an independent risk factor for the development of type 2 diabetes, and strong genetic evidence existed that SHBG is involved in the etiology of type 2 diabetes." (PMID 33101409, 2020). "There was possible pleiotropy in the association of testosterone and SHBG levels (adjusted for BMI) with type 2 diabetes." (PMID 32895727, 2020). "Observational evidence has so far linked higher SHBG levels with lower risk of type 2 diabetes, lower risk of prostate cancer and higher risk of bone loss and fractures." (PMID 32533189, 2020). "Third, single nucleotide polymorphisms in SHBG that downregulate SHBG levels are associated with development of type 2 diabetes, suggesting that SHBG is causal." (PMID 32128321, 2019). "There was little evidence to support associations of genetic liability to type 2 diabetes, parity, or circulating levels of 25-hydroxyvitamin D or sex hormone binding globulin with the various ovarian cancer outcomes assessed." (PMID 31390370, 2019). "Low levels of circulating SHBG are associated with decreased glucose control and are predictors for type 2 diabetes." (PMID 30405702, 2018). "Levels of sex hormone-binding globulin (SHBG) and testosterone have been previously associated with various diseases such as metabolic syndrome, type 2 diabetes and hormone-dependent cancers." (PMID 30547757, 2018). "Given the known association between lower SHBG and higher plasma glucose, our findings suggest a link between socioeconomic disadvantage and future risk of type 2 diabetes." (PMID 28458728, 2017). "Low SHBG concentrations are associated with an increased risk of development of type 2 diabetes mellitus (T2DM)." (PMID 28458728, 2017). "A lower plasma concentration of SHBG correlates with a higher risk for developing metabolic syndrome, type-2 diabetes, and cardiovascular disease." (PMID 27295977, 2016). "This provided the first explanation for why low plasma SHBG is a hallmark of the metabolic syndrome and its associated diseases, such as type 2 diabetes and cardiovascular disease." (PMID 27113851, 2016). "Polymorphisms in the SHBG gene have been associated with risk of type 2 diabetes, suggesting a causal role for SHBG in metabolic disease risk." (PMID 25019163, 2014). "This study investigated the association between circulating SHBG and type 2 diabetes in in a group of Nigerian men." (PMID 29043159, 2013).
type 2 diabetes (continued). "And there is also evidence that mechanisms associated with the SHBG gene is involved in the pathogenesis of type 2 diabetes." (PMID 24069277, 2013). "In a recent study on healthy women, SHBG was suggested as a causal role of developing type 2 diabetes: the lower the levels, the higher the risk." (PMID 23781319, 2013). "SHBG has been linked to chronic diseases including type 2 diabetes and to hormone-sensitive cancers such as breast and prostate cancer." (PMID 22829776, 2012). "SHBG has been associated with chronic diseases including type 2 diabetes (T2D) and with hormone-sensitive cancers such as breast and prostate cancer." (PMID 22829776, 2012). "This is particularly relevant to the relationship between sleep restriction and glucose metabolism, as low levels of endogenous SHBG have been linked with poor glucose tolerance, and conversely, higher levels associated with reduced risk of type 2 diabetes." (PMID 22844441, 2012). "Recent molecular epidemiologic studies mainly from Western populations have reported that genetically determined levels of SHBG were inversely associated with type 2 diabetes risk, lending support to the roles of SHBG in the development of type 2 diabetes." (PMID 23066943, 2012). "Sex hormone-binding globulin (SHBG) levels and sex hormones have been implicated in the pathogenesis of type 2 diabetes and cardiovascular diseases." (PMID 23066943, 2012). "Previous studies have observed that lower levels of testosterone confer greater risk of coronary events and type 2 diabetes in men but lower risk in women, while higher SHBG concentrations protect against coronary disease and type 2 diabetes in both sexes (although to a greater extent in women)." (PMID 40892850, 2025). "SHBG was an independent risk factor for female type 2 diabetes patients." (PMID 39256355, 2024). "However, low SHBG is associated with insulin resistance and type 2 diabetes risk, and mediates the association between intrahepatic fat and type 2 diabetes, with a more significant impact in women." (PMID 36897358, 2023). "Interestingly, low levels of free testosterone and high levels of sex hormone binding globulin (SHBG) were independently associated with mortality in men with type 2 diabetes." (PMID 36897358, 2023). "Low SHBG is a risk factor for type 2 diabetes and cardiovascular disease." (PMID 37794065, 2023). "Although it is assumed that there is a causal association between IHL content, serum SHBG and type 2 diabetes (an assumption that is supported by experimental and genetic studies) we cannot exclude the possibility that the associations are in fact bi-directional." (PMID 36114428, 2023). "However, from this type 2 diabetes data perspective, features such as triglycerides and sex hormone-binding globulin (SHBG) are placed on the same level as those causal biomarkers." (PMID 38096184, 2023). "Most associations of genetically predicted SHBG, with the exception of type 2 diabetes, gout, fracture and endometrial cancer, were largely attenuated after the adjustment for genetically predicted levels of high-density lipoprotein cholesterol and triglycerides." (PMID 35218343, 2022). "Higher genetically predicted SHBG levels were associated with a reduced risk of hypertension, type 2 diabetes, diabetic complications, coronary atherosclerotic outcomes, gout and benign and malignant neoplasm of uterus, but an increased risk of varicose veins and fracture (mainly in females)." (PMID 35218343, 2022). "Moreover, in the 5-year follow-up of 2,077 women, SHBG concentrations were inversely associated with the risk of development of type 2 diabetes." (PMID 35140785, 2022). "Furthermore, another 5-year follow-up study (Environment, Inflammation, and Metabolic Diseases Study) showed that low SHBG levels were associated with 4-fold higher risk of developing type 2 diabetes both in men and women." (PMID 35140785, 2022).
type 2 diabetes (continued). "Previous MR studies suggest SHBG lowers the risk of type 2 diabetes and possibly lowers insulin resistance, so insulin might underlie the protective effect of SHBG in IHD." (PMID 34848757, 2021). "Other studies have also implicated lower SHBG levels in increasing type II diabetes risk." (PMID 34226637, 2021). "Specifically, systolic BP, smoking, insomnia and alanine aminotransferase levels were positively associated with type 2 diabetes, whereas testosterone, SHBG, and HDL- and total cholesterol levels were inversely associated with type 2 diabetes after BMI adjustment." (PMID 32895727, 2020). "Another study reported that SHBG levels were negatively correlated with a risk of type 2 diabetes." (PMID 33291623, 2020). "We used two separate genetic instruments comprising of variants from JMJD1C and SHBG regions and conducted a two-sample Mendelian randomization for type II diabetes (T2D), gout, rheumatoid arthritis (RA), schizophrenia, bipolar disorder, Alzheimer’s disease and depression." (PMID 32610558, 2020). "Low SHBG levels are considered as a consistent marker of type 2 diabetes risk, especially in women." (PMID 29380105, 2018). "In this sample of 141 male patients admitted to undergo coronary angiography in order to diagnose coronary artery disease, at Hospital Dante Pazzanese de Cardiologia, SHBG levels presented significant inverse associations with BMI, abdominal circumference and prevalence of type 2 diabetes." (PMID 24714992, 2014). "In addition, it has been reported that SHBG level was inversely associated with HOMA-IR and that a low SHBG level was associated with the risk of onset of type 2 diabetes in postmenopausal women." (PMID 23825975, 2013). "Furthermore, recent genetic studies provided compelling evidence that genetically determined SHBG levels as well as variants of the SHBG gene are associated with type 2 diabetes risk." (PMID 23066943, 2012). "Findings from observational studies suggest that sex hormone-binding globulin (SHBG) and endogenous sex hormones may be mediators of the putative relation between coffee consumption and lower risk of type 2 diabetes." (PMID 23078574, 2012). "Interestingly, some observational studies find that the protective effects of high circulating SHBG on the risk of ectopic lipid deposition and type 2 diabetes are more pronounced in women compared to men while other studies indicate health related associations with SHBG in both sexes." (PMID 40532849, 2025). "Sex hormone-binding globulin (SHBG) and testosterone are differentially associated with type 2 diabetes (T2D) risk." (PMID 39763542, 2024). "Furthermore, the current data support the concept that increasing serum SHBG (by reduction of IHL content) may be used as a means to reduce type 2 diabetes risk." (PMID 36114428, 2023). "Novel potential intermediate pathways between fitness and type 2 diabetes were also highlighted by the association between genetically predicted fitness and N-terminal pro B-type natriuretic peptide, hepatocyte growth factor-like protein and sex hormone binding globulin." (PMID 37400433, 2023). "Women with PCOS had low levels of SHBG, which binds testosterone and reduces its levels, ameliorating its unwanted effects, including metabolic syndrome, type 2 diabetes, and cardiovascular disease." (PMID 41561041, 2025). "We investigated genetic interactions with three sex hormones (total testosterone, bioavailable testosterone, and sex hormone binding globulin (SHBG)) to identify additional type 2 diabetes-related loci that were undetected in traditional GWAS." (PMID 40892850, 2025). "Research has indicated that sex hormone-binding globulin (SHBG) is associated with glucose homeostasis and may play a role in the etiology of type 2 diabetes (T2D)." (PMID 38954350, 2024).
type 2 diabetes (continued). "In female patients with type 2 diabetes, sex hormone binding globulin (β: -0.154, 95%CI: -0.193, -0.116, p<0.001) decreased, but bioavailable testosterone (β: 0.077, 95%CI: 0.058, 0.096, p<0.001) showed the opposite trend." (PMID 37900148, 2023). "In conclusion, in a large-scale population-based cohort study, we show that serum SHBG is a mediator in the association between IHL content and type 2 diabetes." (PMID 36114428, 2023). "They arise when SHBG’s plasma concentration is decreased, reflecting its role in human metabolism since SHBG concentrations vary in cancer, type 2 diabetes, and dyslipidemia." (PMID 36836833, 2023). "We observed a relatively high estimated proportion of mediation by serum SHBG in the association between IHL content and type 2 diabetes." (PMID 36114428, 2023). "The mediating role of serum SHBG in the association between IHL content and type 2 diabetes was more substantial in women than in men." (PMID 36114428, 2023). "In the present study, serum SHBG partially mediated the association between the IHL content and type 2 diabetes status." (PMID 36114428, 2023). "Mediation analyses were performed to assess the role of serum SHBG in mediating the association between IHL content and type 2 diabetes." (PMID 36114428, 2023). "Nevertheless, this is the first study that has assessed the mediation effect of serum SHBG in the association between IHL content and type 2 diabetes." (PMID 36114428, 2023). "In men, serum SHBG was estimated to mediate 17.2% (95% CI 9.6, 27.6) of the association between IHL content and type 2 diabetes, while the proportion mediated was 50.9% (95% CI 26.7, 81.3) in women." (PMID 36114428, 2023). "In this large-scale population-based cohort study, serum SHBG was found to be a mediator of the association between IHL content and type 2 diabetes." (PMID 36114428, 2023). "In male patients with type 2 diabetes, total testosterone (β: -0.058, 95%CI: -0.088, -0.028, p<0.001) and sex hormone binding globulin (β: -0.097, 95%CI: -0.134, -0.060, p<0.001) decreased." (PMID 37900148, 2023). "The observation in this study of a possible mediating role for sex hormone binding globulin is also supported by strong genetic evidence between sex hormone binding globulin and type 2 diabetes in previous reports." (PMID 37400433, 2023). "Because of that, SHBG is classically seen as a biomarker for such conditions as metabolic syndrome, type 2 diabetes, and cardiovascular diseases." (PMID 36303626, 2022). "In contrast, Mendelian randomization studies have suggested that SHBG is actively involved in the pathogenesis of type 2 diabetes, either directly or via free testosterone." (PMID 34277990, 2021). "A meta-analysis examining different concentrations of SHBG showed that low levels of SHBG in men are a predictor of metabolic syndrome and type 2 diabetes." (PMID 34335746, 2021). "A combined analysis of 23 cross-sectional studies finds that women with type 2 diabetes have significantly lower serum SHBG concentrations than controls." (PMID 34805198, 2021). "Most patients with PCOS are at a high risk for type 2 diabetes and cardiovascular disease (CVD), and serum SHBG concentrations are reported to be altered in PCOS, metabolic syndrome, type 2 diabetes, and CVD." (PMID 34805198, 2021). "Severities of non-alcoholic fatty liver disease were also negatively related to SHBG levels in a study of adult patients with type 2 diabetes." (PMID 33291623, 2020). "Eight exposures were inversely associated with type 2 diabetes: plasma alanine, HDL- and total cholesterol, age at menarche, testosterone levels, SHBG levels (adjusted for BMI), birthweight and adulthood height." (PMID 32895727, 2020). "High plasma estradiol and testosterone, with low SHBG concentrations, have been suggested to be involved in the pathogenesis of type 2 diabetes." (PMID 29682210, 2018).
type 2 diabetes (continued). "The link between concentrations of serum testosterone and type 2 diabetes has become a topic of debate as two prospective studies have shown that SHBG can also independently predict type 2 diabetes." (PMID 26209521, 2015). "While these results are supported by other authors, the role of SHBG in the development of type 2 diabetes is still subject to discussions and its contribution to the development of hypertension has to our knowledge not been investigated at all." (PMID 23594436, 2013). "There is a paucity of studies on the relationship between SHBG and type 2 diabetes in men of African descent." (PMID 29043159, 2013). "Variation in SHBG concentration has also been associated with various chronic diseases including cancers, polycystic ovary syndrome (PCOS) and type 2 diabetes (T2D)." (PMID 22829776, 2012). "In contrast to women, men with type 2 diabetes have low testosterone levels and treatment with rosiglitazone induces an increase in the three fractions of circulating testosterone and SHBG levels." (PMID 20144211, 2010). "Patients with type 2 diabetes often exhibit low levels of testosterone and SHBG, which has been speculated to constitute a protective effect against PCa development." (PMID 41483135, 2026). "Several recent studies have found low levels of sex hormone‐binding globulin (SHBG), a protein produced by the liver that transports testosterone and regulates its bioavailability at the tissue level, in obese individuals, men with type 2 diabetes, and men with NAFLD." (PMID 40313012, 2025). "The relation between low SHBG concentrations andinsulin-resistant states, such as type 2 diabetes and metabolic syndrome, could alsobe involved." (PMID 40857627, 2025). "In most studies, patients with type 2 diabetes have significantly lower total T (TT), free T (FT), and sex-hormone binding globulin (SHBG), with low or inappropriately normal luteinizing hormone (LH) plasma levels, a condition known as hypogonadotropic hypogonadism." (PMID 36282472, 2023). "Concurrently, the lower SHBG level is the predictor of type 2 diabetes." (PMID 36968815, 2023). "It has been suggested that SHBG may play an important role in the pathogenesis of type 2 diabetes by modulating the effects of sex hormones." (PMID 36484476, 2023). "Furthermore, as reported, there was a link between lower SHBG levels and an increased incidence or prevalence of physical diseases, including hypertension, coronary heart disease, type 2 diabetes, PCOS, inflammation, and cancers." (PMID 37091804, 2023). "Second, patients with type 2 diabetes always have lower SHBG levels." (PMID 37900148, 2023). "We performed mediation analyses to assess whether, and to what extent, the relationship between IHL content and type 2 diabetes status was mediated by serum SHBG levels." (PMID 36114428, 2023). "This may be an indication of the biological relevance of serum SHBG in the pathogenesis of type 2 diabetes." (PMID 36114428, 2023). "The current findings corroborate the hypothesis that SHBG may have a role not only as carrier protein for testosterone and a biomarker of metabolic disease, but also as a hepatokine affecting type 2 diabetes." (PMID 36114428, 2023). "Mendelian randomisation studies have shown that genetically predicted low serum SHBG levels are causally associated with an increased risk of type 2 diabetes, independent of the effects of SHBG on free testosterone levels." (PMID 36114428, 2023). "For instance, other unmeasured confounders such as endogenous oestrogens, thyroid hormone or adipokines, which all affect IHL content, serum SHBG levels and type 2 diabetes, may confound the current mediation analyses." (PMID 36114428, 2023).